RHO (rhodopsin)
Diseases named in the same sentence as RHO in open-access papers (continued):
Sharing a sentence is not in itself a finding about the gene and the disease.
osteoporosis (1 paper, 2024). A condition of reduced bone mass, with decreased cortical thickness and a decrease in the number and size of the trabeculae of cancellous bone (but normal chemical composition), resulting in increased fracture incidence. "We found specific osteoporosis-linked SNPs in genes encoding key receptors involved in bone metabolism that are classified into rhodopsin (ADRB2, CNR2, MTNR1B, FSHR, TSHR, LGR4), secretin (CALCR, GIPR), and other T7M (WLS) receptor families." (PMID 39769358, 2024).
ovarian carcinoma (1 paper, 2020). A malignant neoplasm originating from the surface ovarian epithelium. "Finally, the terms “Signaling by Rho GTPases”, “EPHB-mediated forward signaling”, and “RHO GTPase Effectors” related to cross-talk between Ras and Rho signaling, well known as ovarian cancer signaling, were enriched." (PMID 33228226, 2020).
pancreatic cancer (1 paper, 2008). "Overexpressed P-cadherin increases motility of pancreatic cancer cells by interacting with p120ctn and subsequent activation of RHO GTPases." (PMID 18230143, 2008).
prostate carcinoma (1 paper, 2025). A carcinoma that arises from epithelial cells of the prostate gland. "ORA enrichment of these genes showed 16 significant pathways, including many extracellular matrix pathways as well as an RHO GTPase pathway, an oocyte maturation pathway, and a prostate cancer pathway, the latter two of which are perplexing to see in adipose tissue." (PMID 40524488, 2025).
pulmonary fibrosis (1 paper, 2025). Chronic progressive interstitial lung disorder characterized by the replacement of the lung tissue by connective tissue, leading to progressive dyspnea, respiratory failure, or right heart failure. "Key overlapping canonical pathways included the Senescence Pathway, Idiopathic Pulmonary Fibrosis Signaling, ERK5 Signaling, RHO GTPase Cycle, and HGF Signaling." (PMID 40734983, 2025).
renal fibrosis (1 paper, 2021). A final common manifestation of a wide variety of chronic kidney diseases characterized by glomerulosclerosis and tubulointerstitial fibrosis. "Further studies are needed to confirm that stem cells can act through the Notch, Hedgehog, Wnt, JAK/STAT, and RHO/ROCK signaling pathways to treat renal fibrosis." (PMID 34112221, 2021). "The occurrence of renal fibrosis may be associated with the TGF-β/Smad, Notch, Hedgehog, Wnt, TNF-α, NF-κB, MAPK, JAK/STAT, PI3K/AKT, and RHO/ROCK signaling pathways." (PMID 34112221, 2021). "No study has shown that stem cells regulate the Notch, Hedgehog, Wnt, RHO/ROCK, or JAK/STAT signaling pathways to treat renal fibrosis." (PMID 34112221, 2021).
retinal ciliopathy (1 paper, 2017). "Rhodopsin mislocalization is a common phenotypic feature in humans and animal models with retinal ciliopathy." (PMID 29203866, 2017).
retinitis punctata albescens (1 paper, 2011). "Mutations in the RHO gene cause adRP, autosomal recessive RP, ad congenital stationary night blindness, and retinitis punctata albescens." (PMID 21785698, 2011). "Most mutations in the RHO gene cause autosomal dominant or autosomal recessive retinitis pigmentosa and less commonly autosomal dominant congenital stationary night blindness or retinitis punctata albescens." (PMID 21785698, 2011).
skin tumor (1 paper, 2025). "On the other hand, skin tumors were enriched for the certain arms of the GNAQ signaling cascade, namely PI3K/AKT/MTOR signaling and RHO GTPases activating formins." (PMID 40950146, 2025). "The skin tumor was instead enriched for PI3K-AKT-MTOR signaling (p-value < 0.009, FDR < 0.086) and pathways for RHO GTPases activating formins (p-value < 0.002, FDR < 0.058)." (PMID 40950146, 2025).
Stroke (1 paper, 2020). Sudden impairment of blood flow to a part of the brain due to occlusion or rupture of an artery to the brain. "However, it is lacking specific research exploring the possible relationship between stroke and rhodopsin." (PMID 32351353, 2020).
T-cell lymphoma (1 paper, 2019). "In adult T-cell leukemia/lymphoma (ATL), RAC1 is activated by the RHO GEF TIAM1 (T-cell lymphoma invasion and metastasis) and regulates the formation of lamellipodia to enhance tumor cell infiltration." (PMID 31248017, 2019).
vitiligo (1 paper, 2021). Generalized well circumscribed patches of leukoderma that are generally distributed over symmetric body locations and is due to autoimmune destruction of melanocytes. "MAPKAP1 (TOR signaling pathway) promotes dark epithelial pigmentation, GRL101 (rhodopsin signaling pathway) is an ortholog of the pigment dispersing factor, and enolase (glycolysis/gluconeogenesis pathway) is a biomarker of vitiligo, a human pigmentation disorder affecting melanocytes." (PMID 33815466, 2021).
cancer (73 papers, 2011 to 2026). A tumor composed of atypical neoplastic, often pleomorphic cells that invade other tissues. "Other L1CAM-influenced cellular processes such as RNA processing, splicing and the RHO GTPase cycle have also been associated with malignant transformation cancer stemness and radioresistance." (PMID 40429728, 2025). "On the other hand, Reactome enrichment analysis identified RHO GTPase associated signaling pathway to be the main pathway downregulated upon BAY 11-7082 treatment in NRAS mutant cancer cell." (PMID 38982514, 2024). "Escape from apoptosis is a hallmark of cancer, and the RHO GTPase family is also involved in the process of apoptosis." (PMID 36348464, 2022). "What is more, genes negatively correlated with TMEM156 are linked with RHO GTPase effectors, which results in a poorer response to receptor activation, thus reducing cancer cell proliferation, survival, and migration." (PMID 34638224, 2021). "This represents an extra layer of the complexity of the underlying mechanisms involved in RHO-driven cancers, and provides a promising avenue for therapeutic intervention." (PMID 34771549, 2021). "On the other hand, confirming the relevance of RHO modulatory activity on developmental signaling also for cancer, mutations in RHOA have been recently linked to B-cell lymphoma and Burkitt lymphoma via impaired PI3K pathway." (PMID 34124035, 2021). "(iii) How can we incorporate genomic and transcriptomic data from cancer patients with RHO GTPase mutations to establish a lncRNA discovery pipeline to progress preclinical studies to clinical practice?" (PMID 34771549, 2021). "RHO GTPase regulators play a crucial role in RHO GTPase activity and, interestingly, altered expression levels of GEFs, GAPs, and GDIs have been frequently described in human cancer, as well as mutations in a subset of tumors." (PMID 31248017, 2019). "Both typical and atypical RHO GTPases are critical transducers of intracellular signaling and have been linked to human cancer." (PMID 31248017, 2019). "A few of the 69 RHO-specific GEFs in the human genome have been implicated in a small number of cancers." (PMID 27174913, 2016). "Cancers of diffuse histology tend to be ‘genomically stable' implying few mutations or gene amplifications, and prevalent defects in RHO signaling downstream of G-protein-coupled receptors." (PMID 25613731, 2015). "Similarly, RHO GTPases are key signalling molecules associated with cancer hallmarks, while deregulation of the cell cycle is a defining feature of cancer." (PMID 41388088, 2025). "Furthermore, RHO GTPases are regarded as potential diagnostic biomarkers or therapeutic targets for cancer." (PMID 36348464, 2022). "Contrary to recent studies that report the identification of new driver mutations in some RHO GTPases members, such as RAC1, RHOA, and CDC42, analysis of cancer genomes has demonstrated that mutations affecting RHO signaling pathways are found at low frequency in a limited spectrum of tumor types." (PMID 34771549, 2021). "Both typical and atypical RHO GTPases have been implicated in human cancer." (PMID 31248017, 2019). "In addition, RHO GAPs are less appealing for the development of inhibitors because in cancer they are often associated with the loss-of-function mutations and act as tumor suppressors." (PMID 31248017, 2019). "Our findings revealed positively selected mutations in specific RHO pathway genes, a highly variegated gene expression pattern for most of them, and the identification of RHO pathway genes that are important to maintain proliferation rates in a widespread or cancer type-specific manner." (PMID 41480181, 2025). "While mutations in genes encoding RHO GTPases are rare in cancer, alternative mechanisms lead to the spurious activation of RHO pathways, which could add multiple regulatory layers controlling the steady-state levels and activation dynamics of RHO signaling elements." (PMID 34771549, 2021).
cancer (continued). "Functional enrichment analyses revealed disruption of shared cancer- and signaling pathways, including RHO GTPase Cycle, as well as perturbation of pathways specific to vapers or smokers." (PMID 42306798, 2026). "Despite these insights, the prevalence, diversity, and functional consequences of RHO pathway alterations across the landscape of human cancers remain poorly defined." (PMID 41480181, 2025). "Together, our study provides a foundational resource for the cancer and RHO GTPase research communities." (PMID 41480181, 2025). "The toxicity of rhodopsin on normal human cells (IC50 values ranging from 92.59 to 185.18 μmol/L) was slightly lower than the IC50 values of rhodopsin on cancer cells (10 to 80 μmol/L)." (PMID 40711004, 2025). "In this study, we integrated genomic, transcriptomic, and functional dependency data from large-scale public resources to generate the first comprehensive dissection of alterations found in the RHO GTPase signaling landscape across human cancers." (PMID 41480181, 2025). "Notably, mutations in the RHO pathway genes are typically found at low prevalence in cancer genomes, suggesting that altered expression levels or aberrant activation by upstream oncogenic signals may constitute their predominant mode of contribution to tumorigenesis." (PMID 41480181, 2025). "Although our study provides a comprehensive analysis to date of RHO signaling dysregulation in cancer, the readers must be aware that several limitations remain." (PMID 41480181, 2025). "Considering the possibility to target RHO GTPase downstream signaling, and in particular the cancer cell metastatic properties, ROCK has emerged as the most studied downstream effector." (PMID 36766776, 2023). "Fasudil is, so far, the only approved RHO GTPase inhibitor, although in a cancer-unrelated indication (i.e., for the prevention of vasospasm after subarachnoid hemorrhage in Japan)." (PMID 36766776, 2023). "Shared Signaling between a disrupted CSC, MIF-only, and mPR-specific PRG actions included cancer, RHO/GTPases, RNA mechanisms, and autophagy/mitophagy pathways." (PMID 35971177, 2022). "Rhoc, a member of the RHO GTPase family, has been proven to enhance cancer cells migration, invasion, and metastasis through the regulation of cytoskeletal organization." (PMID 35955961, 2022). "RHO GTPases directly control the movement of cancer cell, promoting migration, invasion and metastasis, ultimately leading to the EMT and a switch of cancer cell migration between mesenchymal and amoeboid modes." (PMID 36348464, 2022). "Although the most widespread archetype in the field is that RHO GEFs exert proactive functions in cancer, recent studies in mice and humans are providing new insights into the in vivo function of these proteins in cancer." (PMID 34571765, 2021). "Determination of the modulatory mechanisms of lncRNAs concerning the RHO GTPase signaling pathways is anticipated to substantially expand our knowledge about the mechanisms of cancer progression." (PMID 34771549, 2021). "Typically, high stiffness increases cancer cell migration and invasion through a RHO-ROCK-dependent actin remodeling and reciprocal actomyosin-mediated cell contractility." (PMID 33603134, 2021). "Nevertheless, several questions remain to be addressed: (i) How many lncRNAs are functionally and clinically related to RHO GTPase-driven cancers?" (PMID 34771549, 2021). "Significantly, recent studies have reported that lncRNAs and members of RHO GTPase signaling cascades are dysregulated in various human cancers." (PMID 34771549, 2021). "The clarification of these important issues not only leads to the explanation of many aspects of RHO GTPase activity and their signaling pathways, but also prompts the discovery and development of novel drugs against various diseases, specifically cancer." (PMID 34771549, 2021).
cancer (continued). "From the perspective of the clinical benefits in RHO GTPase-related anti-lncRNA plant-derived natural compounds, credible anti-cancer activity of curcumin was reported through its downregulatory effect on H19." (PMID 34771549, 2021). "(ii) How can systematic genomic and functional approaches be developed to discover the roles of lncRNAs in the initiation and progression of RHO GTPase-mutant cancers?" (PMID 34771549, 2021). "Intriguingly, this analysis also predicted increases in several pathways positively involved in cellular migration and CRC metastasis signaling, including the RHO-GTPase pathway that contributes to cancer progression and metastasis." (PMID 34503224, 2021). "The system is expandable to a range of mutants and allows systematic functional investigation of RHO protein–specific cells and developmental windows of interest and possible crosstalks in fish cancer models." (PMID 34124035, 2021). "The full understanding of the role of RHO GEFs and GTPases in cancer has been historically hijacked by a cell biology-centered vision on their roles in cytoskeletal regulation." (PMID 32963234, 2020). "Aberrant expression levels or mutations of GEFs, GAPs, or GDIs lead to increased activation of RHO GTPase signaling cascades that in turn promote cancer initiation and progression." (PMID 31248017, 2019). "As indicated by our results, the mRNA expression levels of SRC, CDC42, WASL, and RHO were all changed during cancer cell migration." (PMID 28640862, 2017). "Immunofluorescence was also performed for the members of the HIPPO pathway YAP and TAZ as this pathway has been implicated in cancer onset and progression and YAP and TAZ are activated by small GTPases such as RHO." (PMID 27329838, 2016). "Among the 64 RHO-specific GAPs, by contrast, reduced expression in cancer has been found frequently among members of the Deleted in Liver Cancer (DLC) family of Rho-GAPs." (PMID 27174913, 2016). "The RHO family of RAS-related GTPases, which includes CDC42, RAC, and RHO, regulates a variety of proliferative, cytoskeletal, and adhesive functions, and RHO activity is increased in many advanced cancers." (PMID 27174913, 2016). "Of particular interest was the down-regulation of RHO signaling, given the widely known role of RHO dysregulation in cancer." (PMID 26062653, 2015). "Plasticity of cancer cell migration also can be observed as a mesenchymal–amoeboid and amoeboid–mesenchymal through a balance between Rac and Rho signaling and surface protease activity and epithelial–amoeboid transition targeting RHO/ROCK signaling pathways." (PMID 38715921, 2024). "Therefore, both RHO GTPases themselves and downstream effectors are attractive targets for therapeutic drug design in cancer." (PMID 36766776, 2023). "Gene expression profiling revealed enrichment of DEGs in vital cancer-associated signaling pathways such as PI3K-Akt and MAPK-ERK, extracellular matrix reorganization, DNA replication and cell cycle regulation, PTEN regulation, and RHO GTPases formins." (PMID 37745085, 2023). "The RHO GTPases are related to endosomal membrane trafficking in various cell lines and sEV secretion in Oli-neu cells, which is responsible for the regulation of cancer invasion and progression." (PMID 37895140, 2023). "Furthermore, the majority of studies on the roles of RHO GTPase and its regulators in cancer progression have been performed in vitro." (PMID 36348464, 2022). "DLC1 encodes for an RHO GTPase accelerating protein (GAP) that plays a role in the regulation of GTP binding proteins and functions as a potent tumor suppressor gene in several cancers including breast cancer." (PMID 32051475, 2020).